Y_RNA (Y RNA )
Gene: Miscellaneous RNA gene on chromosome 15 (64,445,130 to 64,445,243, reverse strand). Ensembl gene ENSG00000206781.
Homologues: Orthologues: chimpanzee Y_RNA (100% identical), macaque Y_RNA (96% identical). Paralogues in human: RNY1 (88% identical), Y_RNA (87% identical), Y_RNA (86% identical), Y_RNA (85% identical), RNY1P11 (84% identical), Y_RNA (84% identical), RNY1P8 (83% identical), Y_RNA (83% identical), Y_RNA (82% identical), RNY1P5 (82% identical), Y_RNA (81% identical), RNY1P10 (80% identical), and 94 more.